CGAS (cyclic GMP-AMP synthase)
Diseases named in the same sentence as CGAS in open-access papers (continued):
Sharing a sentence is not in itself a finding about the gene and the disease.
cancer (continued). "Chronic activation of cGAS signaling in cancer cells with high chromosomal instability promotes invasion and metastasis, attributed to a switch from IFN-I and canonical NF-κB signaling to non-canonical NF-κB cascades." (PMID 37834184, 2023). "Two studies demonstrated that USP35 deficiency sensitized cancer cells to cisplatin (the first platinum anti-cancer drug) treatment via de-stabilizing anti-apoptotic factor BIRC3 or activating cGAS-STING-TBK1-mediated expression of type I interferons." (PMID 36864055, 2023). "The impact of cGAS-STING targeting drugs in the cancer therapy of RCC remains to be addressed by future studies." (PMID 37190141, 2023). "These hybrids, referred to as R-loops, also stimulate cGAS, and subsequently, IRF3, culminating in apoptosis, especially in BRCA1 (BReast CAncer susceptibility gene 1)-mutated cancer cells in vitro." (PMID 38139802, 2023). "Micronuclei produced by chromosomal instability in cancer cells activate the cGAS/STING innate immune pathway." (PMID 37354378, 2023). "First, we established that in human cancer cell lines defective in their ability to signal through the cGAS/STING pathway, mtRNA is a potent agonist capable of reactivating Type I IFN production and consequent immunosurveillance." (PMID 36918588, 2023). "Recent studies have demonstrated that several conditions in cancer cells contribute to activating the cGAS-STING pathway, such as chromosome mis-segregation during cell division or mitochondrial DNA leakage under the reactive oxygen species (ROS) response." (PMID 37781042, 2023). "The cyclic GMP-AMP synthase-stimulator of interferon genes (cGAS-STING) pathway is critical in cancer immunity." (PMID 36936940, 2023). "Consistent with an active IFN-I response in culture, the metastatic cancer cells displayed elevated levels of cytosolic DNA from both mitochondria and ruptured micronuclei with concomitant activation of cGAS-STING signaling." (PMID 36882786, 2023). "Cancer cells with chromosomal abnormalities or genomic DNA damage often form micronucleus or cytoplasmic chromatin fragments, which can activate the cGAS-STING pathway to initiate a signaling cascade." (PMID 36769349, 2023). "The link between the DNA-damaging activities of traditional cancer therapies and cGAS-STING activation that we have reviewed herein is driving investigations into their application in the cancer immunotherapy setting." (PMID 37627155, 2023). "Currently, several therapeutic approaches aim to stimulate cGAS/STING/IRF3 pathway in cancer to promote an over-stimulation of IFN I." (PMID 36572679, 2022). "Overall, the data are consistent with the activated STING being a positive regulator of NDD at HU-arrested forks in cancer cells, with cGAS as an upstream activator of STING in this context." (PMID 36710880, 2022). "Opposing to this traditional conception, our study suggests that the intrinsic function of cGAS-STING can also play an important role in sustaining viability of cancer cells in hostile growth condition." (PMID 35992877, 2022). "Some limitations of targeting cGAS/STING in cancer exist, including evidence of cGAS/STING silencing or loss-of-function mutations in certain tumors and cGAS/STING-driven IL-6-dependent survival of chromosomally instable cancers." (PMID 36276148, 2022). "As cGAS-STING is often inactivated in cancer, we first tested if the pathway was functional in WM1799 cells." (PMID 35158840, 2022). "Meanwhile, DNA damage caused by cancer treatment leads to an increase in the number of micronuclei in the cytoplasm, which in turn activates cGAS and recruits immune cells to attack cancer cells." (PMID 35536585, 2022). "In conclusion, we systematically analyzed the genetic landscape and biological and clinical relevance of the cGAS-STING signature across human cancers." (PMID 35983076, 2022). "Collectively, it has become clear that the role of the cGAS–STING pathway in cancer is context-dependent, which can be attributed to several factors." (PMID 35325182, 2022).
cancer (continued). "On the other hand, cyclic GMP-AMP synthase (cGAS) is the central cytosolic double-stranded DNA (dsDNA) sensor that recognized the self-DNA from the dying cells (cancer cells), allowing the innate immune system to respond against the abnormal cells." (PMID 36142859, 2022). "Recently, the importance of the DNA damage response (DDR), and its interplay with the cGAS-STING axis in cancer immunity/immunotherapy is attracting attention." (PMID 36559204, 2022). "In our study, cytotoxic CD8 + T cells were distributed within the stromal tissue in stromal-STING-dominant cases, and their recruitment to cancer cells was lower than in cases which cGAS-STING was expressed in cancer cells." (PMID 35773436, 2022). "Simultaneously, DNA damage also produces these micronuclei and triggers the cGAS-STING pathway in cancer cells." (PMID 35741087, 2022). "The role of cyclic GMP-AMP synthase (cGAS)-stimulator of interferon genes (STING) signaling pathway in cancer immunity has been increasingly recognized in recent years." (PMID 36442099, 2022). "Self DNA from dying or damaged cancer cells, as an important danger DAMPs signal, triggers the cGAS-STING signaling pathway to induce IFNs, which is critical for intrinsic antitumor immunity." (PMID 35983076, 2022). "Our results further demonstrate that MUC1-C is necessary for constitutive expression of cGAS, which is activated by the cytosolic accumulation of DAMPs that are the products of genomic instability in cancer cells." (PMID 35681561, 2022). "Article keywords demonstrated that scholars in the fields of cancer and neuroscience should pay more attention to the cGAS-STING pathway because these were hotspots in recent years." (PMID 35720348, 2022). "Recent studies have shown that the cGAS-STING pathway is closely related to cancer development and progression." (PMID 35563740, 2022). "Micronuclei were shown to mediate the activation of type I Interferon (IFN) and IFN-stimulated genes (ISG) in cancer cells through the cGAS-STING signalling pathway." (PMID 35794238, 2022). "Overall, the current study unveils an unexpected function of the cGAS-STING axis in promoting cancer cell survival and demonstrates the potential of developing the stress-responding pathway as a therapeutic target." (PMID 35992877, 2022). "The capability of the cGAS-STING score in predicting the prognosis of cancer patients was also validated." (PMID 35983076, 2022). "MCF7 cybrids were treated with cisplatin and analyzed for cell viability, mitochondrial membrane potential, ROS, and expression levels of genes associated with the cGAS-STING and cancer-related pathways." (PMID 35743133, 2022). "As a major innate immunity pathway that detects cancer cells and activates antitumor immune responses, the cGAS-STING pathway has been an attractive target for developing therapeutics to improve the outcome of cancer treatments." (PMID 36442099, 2022). "The importance of cGAS-STING signaling in cancer has been evidenced in many preclinical models, both in vivo and in vitro." (PMID 35773436, 2022). "Since this inflammatory response to aneuploidy and CIN seems to be genoprotective, e.g., by fostering NK cell recognition, it is puzzling that cGAS and STING, while often lowly expressed in cancer cell lines, are rarely mutated (<1%) in cancer." (PMID 36612027, 2022). "Stimulator of interferon genes (STING) functions downstream of cyclic GMP-AMP synthase in DNA sensing or as a direct receptor for bacterial cyclic dinucleotides and small molecules to activate immunity during infection, cancer and immunotherapy." (PMID 36261523, 2022). "Recent advances in research suggest that the cGAS-STING pathway is involved in different parts of the cancer-immunity cycle (CIC) to promote or suppress antitumor immune responses." (PMID 36353640, 2022). "Recent studies indicate that targeting DDR can improve cancer immunotherapy by modulating the immune response mediated by cGAS-STING-interferon signaling." (PMID 35328658, 2022).
cancer (continued). "By defining cGAS-STING activation status on a pan-cancer level using genes with known roles in the pathway, we were able to build a gene expression–based model of cGAS-STING activation based on unsupervised clustering." (PMID 36923311, 2022). "In light of the importance of the cGAS-STING pathway in cancer immunity, considerable efforts have been undertaken to target this pathway pharmaceutically." (PMID 36442099, 2022). "Due to the important mechanism in fuelling the development of inflammation and immune response, the cGAS-STING pathway has emerged as a critical regulator of cancer development." (PMID 35983076, 2022). "Taken together, the results indicated that the cGAS-STING signal was tightly correlated with the extent of immune infiltration in cancers." (PMID 35983076, 2022). "Actually, in some cancer cells, epigenetic silencing and oncogenic signals lead to the inactivation of cGAS-STING pathway, participating in immune escape." (PMID 36209176, 2022). "Most patients with CRC exhibited weak cGAS expression in cancer cells, and 43.2% of patients with CRC lost cGAS expression in cancer cells (112/259 = 43.2%)." (PMID 35835756, 2022). "Remarkably, the cancer cell-intrinsic cGAS-STING pathway, which is activated by RT, promotes immune evasion by upregulating programmed cell death-ligand 1 (PD-L1)." (PMID 36139006, 2022). "According to KEGG databases and related studies, using a 5-gene cGAS-STING signature, we identified the activity of the cGAS-STING pathway in many cancer types based on the data of TCGA." (PMID 35983076, 2022). "The activation of cGAS-STING in cancer cells can enhance the production of type I interferon which then exerted potent effects on the priming of antitumor T cells." (PMID 35847556, 2022). "cGAS gene expression is well correlated in many cancer types, while TBK1 and IRF3 gene expression is correlated with immune cells presence and interferon response only in few specific cancer types." (PMID 35794238, 2022). "Combined expression analysis of cGAS and STING showed a significantly higher percentage of patients with MSI-H mCRC with a fully or partially activated cGAS-STING signalling pathway in cancer cells (chi-square test, p = 0.0050)." (PMID 36612217, 2022). "It has previously been shown that ATRX is involved in the activation of the cGAS-STING DNA sensing pathway in cancer cells that use the ALT pathway to maintain telomere length." (PMID 35939517, 2022). "cGAS recognizes dsDNA in micronuclei and the localization of cGAS to micronuclei is induced by genome instability in a mouse model of monogenic autoinflammation and in human cancer cells with exogenous DNA damage." (PMID 34374004, 2022). "The early preclinical studies investigating the role of cGAS–STING signaling in cancer identified its role vis-à-vis type I IFN response." (PMID 35325182, 2022). "Micronuclei, which commonly lack intact nucleoskeletal structures, are particularly prone to irreversible rupture, and thus cGAS localization to micronuclei is frequently observed in cancer cells." (PMID 35468978, 2022). "Even though STING agonists have demonstrated good application prospects, the clinical application of the cGAS-STING signal pathway in cancer treatment is limited at present." (PMID 35889509, 2022). "Numerous studies are currently investigating the preclinical implications of the cGAS/STING pathway in cancer and how other mediators of this pathway can be modulated to promote pro-immune, antitumor effects." (PMID 36387071, 2022). "The pan-cancer landscape of cGAS-STING expression was calculated using the RNAseq data acquired from the TCGA cohort." (PMID 35983076, 2022). "For a better understanding of machinery, we describe detailed mechanisms of each telomere maintenance and the cGAS-STING pathway in cancer regulation in the next chapters." (PMID 35741087, 2022).
cancer (continued). "Future efforts to depict a more detailed picture of the roles of cGAS–STING signaling in the TME will help design a better cancer treatment regime by targeting the cGAS–STING pathway more precisely." (PMID 35325182, 2022). "Cancer-immune cell co-culture experiments demonstrated that downregulation of the cGAS–STING pathway in cancer cells induces resistance to immune effectors." (PMID 35734577, 2022). "In this study, we first investigated the expression of cGAS in solid tumors and its relationship with the prognosis of cancer patients using in silico analysis." (PMID 35563740, 2022). "Cancer cases were divided into high-expression and low-expression groups based on the score of cGAS-STING gene signature, and correlation between the level of cGAS-STING score and the prognosis of patients was investigated." (PMID 35983076, 2022). "It was shown that genomic instability can lead to activation of the cGAS/STING signaling pathway in cancer cells." (PMID 36125896, 2022). "We, for the first time, showed that RocA promoted STING-dependent infiltration and antitumor immunity of NK cells by targeting mtDNA, suggesting that RocA had a promising potential in cancer immunotherapy as a potent agonist of cGAS-STING." (PMID 35002511, 2022). "Dysregulation of the cGAS-STING pathway has been related to many disorders including infections, inflammatory diseases, neurodegeneration, cancers and aging-associated diseases." (PMID 34676498, 2022). "In tumors, type I interferons are secreted by cancer cells and dendritic cells (DCs) in response to DNA fragments that activate the cGAS/STING pathway and result in T cell priming and antitumor activity." (PMID 36428720, 2022). "Extranuclear DNA foci, sometimes in the form of micronuclei, can be observed in some cancer cells and have been shown to bind cGAS." (PMID 35670106, 2022). "Given the finding of the cGAS-STING-mediated growth advantage, our results highlight the potential complications of the popular approaches to enhance the activity of the cGAS-STING axis as a means of anti-cancer therapy." (PMID 35992877, 2022). "The cyclic GMP-AMP synthase (cGAS) is one of the major PRRs to detect cytosolic DNA in cancer cells." (PMID 35328658, 2022). "The innate immune cyclic GMP-AMP synthase (cGAS)/stimulator of interferon genes (STING) pathway has recently emerged as a nodal player in cancer immunity and is currently being explored as a potential therapeutic target." (PMID 35967414, 2022). "The activation of the cGAS pathway in immune cells is known to induce antitumor effects, but the role of cGAS in cancer cells remains poorly understood." (PMID 35563740, 2022). "How do cancer cells with CIN cope with the potentially deleterious effect of cGAMP export given that they exhibit constitutive cGAS activation in response to genomic instability?" (PMID 35325182, 2022). "There are numerous preclinical studies of cGAS-STING activators designed to treat cancer, and some designed to treat autoimmune diseases." (PMID 35741054, 2022). "Kaplan–Meier curves, Cox regression analyses, and the area under the curve (AUC) were employed to decipher the predictive value of cGAS-STING risk score and TIICs across several human cancers." (PMID 35983076, 2022). "It helps to better understand the dysregulation of the cGAS-STING pathway in cancers, especially KIRC, KIRP, and PCPG." (PMID 35983076, 2022). "Given the importance of cGAS in the DNA recognition pathway, it plays a crucial role in both aspects of cancer." (PMID 35185917, 2022). "Although the impacts of Saccharomyces cerevisiae on cancers are mentioned, data on its use in mice with cyclic GMP-AMP synthase deficiency (cGAS-/-) are even rarer." (PMID 36142859, 2022). "TMPs are microparticles produced by apoptotic cancer cells that promote the production of IFN-I by activating the cGAS-STING signaling pathway." (PMID 35844623, 2022).
cancer (continued). "Here, we used combined expression data from 2,307 tumors from five cancer types from The Cancer Genome Atlas to define a novel cGAS-STING activity score based on eight genes with a known role in the pathway." (PMID 36923311, 2022). "Hypermethylation of cGAS/STING promoters contributes to the transcriptional silencing and perturbed STING signalling function is implicated in various cancers." (PMID 35903542, 2022). "We first analyzed the expression of cGAS mRNA across different types of cancer cells from the Cancer Cell Line Encyclopedia." (PMID 35563740, 2022). "As activated T cells release EVs containing mtDNA and activate the cGAS-STING pathway in dendritic cells, it is possible that cancer cells also activate the cGAS-STING pathway by importing mtDNA from EVs secreted by surrounding cells." (PMID 35741087, 2022). "Taken together, these results suggest that the activation of the cGAS pathway in immune cells is valuable for cancer treatment, and that the cGAS pathway is a potential therapeutic target for the induction of antitumor effects in cancer therapy." (PMID 35563740, 2022). "This supports a model where CIN in tumors with active cGAS-STING pathway creates an inflamed local environment with increased immune cell infiltration of the carcinoma cells." (PMID 36923311, 2022). "Although DNA sensing by cGAS-STING plays a major role in the response to cancer therapy it should be noted that RNA in various forms can contribute to the inflammatory response under conditions that challenge genome integrity." (PMID 34249949, 2021). "The cGAS-STING pathway acts as a cDNA detector that activates the immune responses against cancer cells." (PMID 34858438, 2021). "Nevertheless, in contrast to its role in triggering the SASP phenotype by free DNA, cGAS-STING-mediated DNA autophagy in cancer cells has rarely been evaluated." (PMID 34123836, 2021). "The cytoplasmic double strand DNA of cancer cells binds to and activates cGAS, an enzyme that catalyzes the production of cyclic GMP-AMP (cGAMP), which is a type of cyclic dinucleotide that binds to and activates STING." (PMID 34768716, 2021). "For example, the cGAS–STING pathway was demonstrated to have a role in cancer and lipid metabolism as well as in a range of chronic inflammation-related diseases in various organs." (PMID 34906241, 2021). "ATR inhibition can further increase cGAS-positive micronuclei and cytokine production in PARPi-treated cancer cells." (PMID 34970273, 2021). "It is worth noting that the cGAS-STING pathway is defective in many cancer types, including melanoma and colorectal cancer." (PMID 34867409, 2021). "Based on the critical role of the cGAS-STING signal pathway in the development of cancer, there are increasing studies have begun to focus on the treatment of tumors with agonists/drugs related to this pathway in recent years." (PMID 34956229, 2021). "Cytosolic DNA stimulated secretion of IFN-β by cancer cells following activation of the DNA sensor cGAS and its downstream effector STING." (PMID 34830880, 2021). "Based on these findings, many preclinical studies have begun to use direct pharmacological stimulation of the cGAS-STING signal pathway as a new way to treat cancer." (PMID 34956229, 2021). "cGAS-STING chronic activation and its downstream effectors, for instance, TBK1, have been associated with inflammation persistence and cancer progression." (PMID 34519260, 2021). "The importance of cytosolic DNA-stimulated immune responses in the context of cancer therapy is highlighted by the contribution of cGAS/STING to antitumor immunity in response to radiotherapy." (PMID 33888558, 2021). "In cancer pathogenesis, DNA leaks from the nucleus due to rapid proliferation and is present in the cytoplasm, which serves as a substrate for cGAS to produce cGAMP." (PMID 34445736, 2021).